SEC61G (SEC61 translocon subunit gamma)
Description:
Component of SEC61 channel-forming translocon complex that mediates transport of signal peptide-containing precursor polypeptides across the endoplasmic reticulum (ER) (By similarity). Forms a ribosome receptor and a gated pore in the ER membrane, both functions required for cotranslational translocation of nascent polypeptides (By similarity). The SEC61 channel is also involved in ER membrane insertion of transmembrane proteins: it mediates membrane insertion of the first few transmembrane segments of proteins, while insertion of subsequent transmembrane regions of multi-pass membrane proteins is mediated by the multi-pass translocon (MPT) complex. The SEC61 channel cooperates with the translocating protein TRAM1 to import nascent proteins into the ER (By similarity).
Synonyms: SSS1
Tractability: Small molecule: a structure with a bound ligand is known. Antibody: UniProt predicts a signal peptide or a membrane-spanning region. PROTAC: ubiquitination databases record sites on it; its protein half-life has been measured.
Gene: Protein-coding gene on chromosome 7 (54,752,180 to 54,759,974, reverse strand). Ensembl gene ENSG00000132432.
Subcellular location: Endoplasmic reticulum membrane
Pathways (Reactome):
Immune System: ER-Phagosome pathway
Metabolism of proteins: SRP-dependent cotranslational protein targeting to membrane
Protein localization: Insertion of tail-anchored proteins into the endoplasmic reticulum membrane
Gene Ontology:
Molecular function: protein binding; ribosome binding; protein transmembrane transporter activity
Biological process: SRP-dependent cotranslational protein targeting to membrane, translocation; post-translational protein targeting to membrane, translocation; protein targeting to ER; intracellular protein transport; protein targeting; protein transmembrane transport; protein transport
Cellular component: endoplasmic reticulum membrane; membrane; Sec61 translocon complex; cytosol; Ssh1 translocon complex
Genetic constraint (gnomAD): Loss-of-function variants: 1 observed, 2.51 expected, observed/expected ratio (o/e) 0.4, 90% interval 0.14 to 1.62. That is too few expected variants to judge how well the gene tolerates losing a copy. Missense variants: 29 observed, 40.44 expected, observed/expected ratio (o/e) 0.72, 90% interval 0.53 to 0.98. Synonymous variants: 10 observed, 12.49 expected, observed/expected ratio (o/e) 0.8, 90% interval 0.49 to 1.36.
Homologues: Orthologues: chimpanzee SEC61G (100% identical), dog SEC61G (100% identical), guinea pig SEC61G (100% identical), macaque SEC61G (100% identical), mouse Sec61g (100% identical), pig SEC61G (100% identical), rabbit SEC61G (100% identical), rat Sec61g (100% identical), zebrafish sec61g (100% identical), tropical clawed frog sec61g (97% identical), rat AABR07067441.3 (96% identical), rat AABR07028668.1 (90% identical), and 5 more.
Diseases named in the same sentence as SEC61G in open-access papers:
SEC61G is named in the same sentence as 41 diseases in open-access papers, as found by Europe PMC text mining. Sharing a sentence is not in itself a finding about the gene and the disease. The quoted sentences say what the papers report.
glioblastoma (22 papers, 2010 to 2025). The most malignant astrocytic tumor (WHO grade IV). "Due to its strong association with immune evasion in glioblastoma, we used bioinformatics databases to investigate the relationship between SEC61G and immunostimulation as well as immune cell infiltrations." (PMID 37893092, 2023). "A recent study also demonstrated that high SEC61G expression is associated with worse OS in glioblastoma, which was consistent with our study." (PMID 34590792, 2021). "On the basis of the statistical analysis of sequencing data from the Cancer Genome Atlas (TCGA) and the Chinese Glioma Genome Atlas (CGGA) cohorts, researchers have shown that high SEC61G expression is significantly associated with poor prognosis in glioblastoma patients." (PMID 40535761, 2025). "In addition, some studies associated SEC61G overexpression with worse survival in hepatocellular carcinoma, head and neck squamous carcinoma, glioblastoma and lung adenocarcinoma." (PMID 37489460, 2023). "In several cancers, including breast cancer, head and neck squamous cell carcinoma, glioblastoma, and kidney cancer, SEC61G is overexpressed and acts as a cancer promoter [6‒9]." (PMID 38978503, 2024). "Deletion of SEC61G in mouse glioblastoma induced increased infiltration of CD8+ cytotoxic T cells in TME." (PMID 37893092, 2023). "There exists a potential correlation between SEC61G expression and the outcome of temozolomide treatment and radiotherapy for glioblastoma patients." (PMID 34173014, 2022). "It was also reported that high expression of the SEC61G gene was correlated with a poor prognosis of glioblastoma patients in a study that used the TCGA and CGGA (Chinese Glioma Genome Atlas) datasets." (PMID 34173014, 2022). "It has been reported that there is a higher level of SEC61G in the tissues of glioblastoma multiforme than in those of lower-grade gliomas." (PMID 34173014, 2022). "More recently, SEC61G was found to be overexpressed in gastric cancer, breast cancer, and glioblastoma 10-12." (PMID 34093796, 2021). "Several studies have demonstrated that SEC61G was overexpressed in Glioblastoma, gastric cancer, hepatocellular carcinoma and breast carcinomas." (PMID 34774014, 2021). "A recent study indicates that SEC61G overexpression was an inferior prognostic factor in glioblastoma multiforme." (PMID 34590792, 2021). "SEC61G gene was also found to coamplify with epidermal growth factor receptor in patients with glioblastoma and served as a potential prognostic marker." (PMID 34774014, 2021). "SEC61G encodes a subunit of a heterotrimeric protein channel located in the endoplasmic reticulum and it has been shown that silencing of SEC61G expression in glioblastoma cells led to growth suppressiio and apoptosis." (PMID 21170331, 2010). "SEC61G may be used as a new prognostic marker for predicting the survival and treatment response of patients with glioblastoma." (PMID 40535761, 2025). "Some published studies have reported that SEC61G may serve as a prognostic indicator in different types of cancer, including glioblastoma (GBM), hepatocellular carcinoma (HCC), and kidney cancer." (PMID 37893092, 2023). "In addition, SEC61G was identified as a novel prognostic marker to predict survival and treatment response in glioblastoma patients in recent studies." (PMID 36531217, 2022). "It was reported that the response to ER stress might contribute to the oncogenic role of SEC61G in glioblastoma." (PMID 34173014, 2022). "A recent study further demonstrated that SEC61G could function as a novel prognostic biomarker to predict survival and response to therapies in glioblastoma patients." (PMID 34039955, 2021). "Multiple studies have suggested that SEC61G is highly expressed in glioblastoma and inhibition of SEC61G could be a promising therapeutic strategy for glioblastoma." (PMID 34039955, 2021). "SEC61G is a proto-oncogene required for glioblastoma cell survival." (PMID 33936159, 2021).
glioblastoma (continued). "On the other hand, SEC61g over-expression is considered a parameter of bad glioblastoma prognosis." (PMID 33020388, 2020). "Interestingly, a recent study revealed that SEC61G can play a role in helping EGFR-amplified glioblastoma (GBM) to evade host immune elimination." (PMID 37893092, 2023). "Our study showed that SEC61G was upregulated in LUAD tissues compared with adjacent normal tissues in the TCGA-LUAD cohort, which was consistent with previous studies founded in glioblastoma and hepatocellular carcinoma." (PMID 34774014, 2021). "Specifically, both subclonal lines EPP-MI and EPP(#1)-MI express the product of the fusion gene SEC61G-EGFR, which resembles the oncogenic EGFRvIII found in glioblastoma from both structural and functional standpoints." (PMID 33668642, 2021). "VSTM2A, LANCL2, SEC61G and VOPP1 were also amplified and are reported in the literature as fusion genes with EGFR in some glioblastoma patients." (PMID 29844869, 2018). "A recent study investigating glioblastoma has provided evidence for the negative modulatory function of SEC61G." (PMID 37893092, 2023).
breast carcinoma (13 papers, 2021 to 2025). "In studies conducted for breast cancer, it has been stated that the SEC61G gene can be used as a diagnostic biomarker and therapeutic target, since high expression of SEC61G is associated with the expression of the proliferation marker Ki-67 and glycolysis." (PMID 37489460, 2023). "Then, to verify overexpression of SEC61G was an independent risk factor for disease-specific survival of breast cancer patients, multivariate analysis was made." (PMID 35154452, 2022). "Loss-of-function analysis indicated that SEC61G knockdown can decrease the migration and invasion of breast cancer cells in vitro." (PMID 35154452, 2022). "Interestingly, SEC61G is reportedly linked to metabolic reprogramming, such as glucose metabolism and glycolysis, in breast cancer cells." (PMID 38978503, 2024). "Intriguingly, Pearson correlation analysis of TCGA BRCA cohort found that SEC61G expression was positively associated with proliferation marker Ki-67 expression, suggesting that upregulated SEC61G expression in breast cancer might be correlated with a high rate of cancer cell proliferation." (PMID 34039955, 2021). "Previous studies have shown that SEC61G promotes tumor invasion through metabolic regulation in breast cancer, and its role in glycolysis is consistent with these findings." (PMID 39990664, 2025). "Previous studies have indeed suggested that SEC61G can serve as an effective marker for predicting worse prognosis in several cancer types, including lung cancer, breast cancer, kidney cancer, head and neck cancer, and hepatocellular carcinoma (HCC)." (PMID 37893092, 2023). "Another study reported that SEC61G manipulates the proliferation and metastasis of breast cancer cells by affecting the epithelial–mesenchymal transition (EMT) process." (PMID 37893092, 2023). "We assessed SEC61G expression level between breast cancer cell lines and normal breast cell lines through RT-qPCR." (PMID 35154452, 2022). "We performed proliferation, colony formation, migration, invasion assays, and EMT-related phenotype to determine the specific biological functions of SEC61G in breast cancer cell lines (MDA-MB-231, BT-549) transfected with small interfering RNA." (PMID 35154452, 2022). "Metastasis is a principal characteristic of the tumor, then we inspected the influence of SEC61G on the migration and invasion of breast cancer cells." (PMID 35154452, 2022). "HOXD10, HOXA5, and SEC61G have all been shown to play an important role in breast tumorigenesis and were identified as potential biomarkers for the diagnosis of breast cancer." (PMID 36531217, 2022). "By analyzing the molecular characteristics of SEC61G, we found that SEC61G was altered by 1.2% in the tested breast cancer samples." (PMID 35154452, 2022). "We also studied the purpose of SEC61G in breast cancer cell lines via small interfering RNA (si-RNA), as well as analyzed the association amongst SEC61G expression and clinical features." (PMID 35154452, 2022). "E2F1, as the transcription factor directly bound to the promoter and regulate the expression of SEC61G, has been validated in breast cancer." (PMID 36712687, 2022). "This study revealed that SEC61G plays vital tumorigenic functions and acts as a novel oncogene in breast cancer." (PMID 35154452, 2022). "Upregulation of SEC61G also promote cell invasion, and migration via modulating glycolysis in breast cancer." (PMID 36712687, 2022). "To know the relation among SEC61G and breast cancer clearly, we examined the relationship of SEC61G with clinicopathologic qualities." (PMID 35154452, 2022). "Our analysis also found that SEC61G is significantly overexpressed in multiple malignancies in the TCGA database, such as gastric, liver cancer and breast carcinomas." (PMID 34774014, 2021). "SEC61G expression was significantly higher in breast cancer compared with that in normal tissues (P = 0.013)." (PMID 34039955, 2021).
breast carcinoma (continued). "The results indicated that glycolysis signaling was significantly enhanced in breast cancer patients with upregulated SEC61G expression." (PMID 34039955, 2021). "Functionally, we demonstrated that knockdown of SEC61G suppressed breast cancer cell proliferation, migration, invasion, and promoted breast cancer cell apoptosis in vitro." (PMID 34039955, 2021). "We also confirmed that breast cancer tissues had markedly higher expression of SEC61G in the NMU breast cancer (NMU BRCA) cohort (n = 35, P < 0.001)." (PMID 34039955, 2021). "SEC61G promoted breast cancer cell malignancy behavior both in vitro and in vivo, which functioned as an oncogene in breast cancer." (PMID 34039955, 2021). "To study the function of SEC61G in vitro, we examined the expression of SEC61G in different breast cancer cell lines and normal breast epithelial cell line MCF-10A." (PMID 34039955, 2021). "Thus, SEC61G could be used as a diagnostic biomarker and therapeutic target for breast cancer." (PMID 34039955, 2021). "Future studies are needed to investigate the detailed signaling pathways involved in the E2F1/SEC61G axis regulating breast cancer development." (PMID 34039955, 2021). "The wound-healing assay revealed that knockdown of SEC61G suppressed breast cancer cell migration, while transwell assay demonstrated that silencing SEC61G inhibited breast cancer cell invasion." (PMID 34039955, 2021). "Cell apoptosis in breast cancer cells with SEC61G knockdown was analyzed by Annexin V/7-AAD staining and the results showed that knockdown of SEC61G significantly enhanced breast cancer cell apoptosis." (PMID 34039955, 2021). "Mechanistically, we showed that transcription factor E2F1 directly bound to the promoter of SEC61G and regulated its expression in breast cancer cells." (PMID 34039955, 2021). "Taken together, our findings demonstrate that SEC61G promotes breast cancer development and metastasis via modulating glycolysis and is transcriptionally regulated by E2F1." (PMID 34039955, 2021). "In vitro cellular function experiments were carried out and the results suggested that knockdown of SEC61G using si-SEC61G-2 also suppressed breast cancer cell proliferation, migration, and invasion, with less efficiency compared with that of si-SEC61G-3." (PMID 34039955, 2021). "The oncogenic role of SEC61G in breast cancer was validated in both in vitro functional assays and in vivo xenograft tumor model." (PMID 34039955, 2021). "By analyzing The Cancer Genome Atlas breast cancer cohort, we found that SEC61G was highly expressed in breast cancer and predicted poor prognosis of breast cancer patients." (PMID 34039955, 2021). "In this study, we demonstrated that SEC61G was overexpressed in breast cancer and high expression of SEC61G predicted the poor outcome of breast cancer patients." (PMID 34039955, 2021). "SEC61G overexpression antagonized the effect of E2F1 knockdown in regulating breast cancer cell proliferation, invasion, and apoptosis." (PMID 34039955, 2021). "Nevertheless, the expression pattern and function of SEC61G in breast cancer have not been fully understood." (PMID 34039955, 2021). "To investigate the function of SEC61G in breast cancer, we first analyzed the expression of SEC61G in The Cancer Genome Atlas Breast Cancer (TCGA BRCA) cohort." (PMID 34039955, 2021). "Furthermore, they demonstrated that overexpression of SEC61G contributes to the development and metastasis of breast cancer by modulating glycolysis, a process regulated by the transcription factor E2F1." (PMID 37878007, 2023). "The immune infiltration analysis indicated that SEC61G might affect tumor immunity, which might guide the immunological therapy of breast cancer." (PMID 35154452, 2022). "In the summary, SEC61G is one of the up-regulated genes in breast cancer." (PMID 35154452, 2022).
breast carcinoma (continued). "And the survival curves of SEC61G were drawn, which reminded us that higher expression of SEC61G predicted poor overall survival, poor disease-specific survival, and poor progress-free interval of breast cancer patients." (PMID 35154452, 2022). "We found SEC61G downregulation could remarkably weaken N-cadherin and Vimentin expression and enhance E-cadherin expression in breast cancer cells." (PMID 35154452, 2022). "These further validated that SEC61G was overexpressed in breast cancer and may function as an oncogene in breast cancer." (PMID 35154452, 2022). "The present study targeted to demonstrate the function of the SEC61G gene in breast cancer." (PMID 35154452, 2022). "These outcomes confirmed that SEC61G as an oncogene could affect metastasis in a breast cancer cell." (PMID 35154452, 2022). "Moreover, down-regulated SEC61G impaired the proliferation of breast cancer cell lines which was consistent with our previous outcomes and promoted apoptotic cell death in breast tumor cells." (PMID 35154452, 2022). "These indicated that a high expression level of SEC61G might predict a poor prognosis of breast cancer." (PMID 35154452, 2022). "We investigated that SEC61G was higher in breast cancer tissues associated to adjacent non-tumor tissues through qRT-PCR." (PMID 35154452, 2022). "Since we found that the expression of SEC61G and tumor size were statistically significant in TCGA, we wonder if SEC61G could affect the proliferation of breast cancer cell lines." (PMID 35154452, 2022). "We aimed to investigate the expression and function of SEC61G in breast cancer." (PMID 34039955, 2021). "Taken together, our findings suggest that SEC61G could be utilized as a novel therapeutic target for breast cancer treatment." (PMID 34039955, 2021). "Furthermore, high SEC61G expression in breast cancer patients with tumor, nodes, and metastases (TNM) stage I–II or TNM III–IV also exhibited markedly lower rates of overall survival and disease-free survival compared with patients with low SEC61G expression." (PMID 34039955, 2021). "Here we revealed the oncogenic role of E2F1 in breast cancer via enhancing SEC61G expression." (PMID 34039955, 2021). "Finally, we demonstrated that the E2F1/SEC61G axis regulated glycolysis and chemo-sensitivity of Herceptin in breast cancer cells." (PMID 34039955, 2021). "Here we further demonstrate that SEC61G was highly expressed in breast cancer." (PMID 34039955, 2021). "Breast cancer tissues had much higher expression of SEC61G than that in normal tissues." (PMID 34039955, 2021). "Moreover, we revealed that the E2F1/SEC61G axis modulated glycolysis and Herceptin chemo-sensitivity in breast cancer cells." (PMID 34039955, 2021). "Knocking down SEC61G might decrease the invasive capability of breast cancer cell lines." (PMID 35154452, 2022). "SEC61G might affect tumor immunity, which might guide the immunological therapy of breast cancer." (PMID 35154452, 2022). "Taken together, these results of in vitro and in vivo studies demonstrate that SEC61G promotes breast cancer development and metastasis via modulating glycolysis and is transcriptionally regulated by E2F1, which might be utilized as a promising therapeutic target of breast cancer treatment." (PMID 34039955, 2021). "Thus, SEC61G could antagonize the effect of E2F1 knockdown in regulating breast cancer cell proliferation, invasion, and apoptosis." (PMID 34039955, 2021). "Furthermore, we demonstrated that SEC61G positively regulated glycolysis in breast cancer cells." (PMID 34039955, 2021). "Thus, knockdown of SEC61G inhibited breast cancer xenograft tumor development in vivo." (PMID 34039955, 2021). "Thus, SEC61G could be utilized as a novel biomarker and therapeutic target for breast cancer treatment." (PMID 34039955, 2021).